SLC4A5 (solute carrier family 4 member 5)
Description:
Mediates sodium- and bicarbonate-dependent electrogenic sodium bicarbonate cotransport, with a Na(+):HCO3(-) stoichiometry varying from 1:2 to 1:3.
Synonyms: NBC4; NBCe2
Tractability: Antibody: UniProt places it where antibodies can reach, with high confidence; its Gene Ontology location is reachable by antibodies, with high confidence; UniProt predicts a signal peptide or a membrane-spanning region. PROTAC: ubiquitination databases record sites on it.
Gene: Protein-coding gene on chromosome 2 (74,216,242 to 74,343,416, reverse strand). Ensembl gene ENSG00000188687.
Subcellular location: Apical cell membrane; Basolateral cell membrane
Pathways (Reactome):
Transport of small molecules: Bicarbonate transporters
Gene Ontology:
Molecular function: sodium:bicarbonate symporter activity; bicarbonate transmembrane transporter activity; monoatomic anion transmembrane transporter activity; secondary active transmembrane transporter activity; solute:inorganic anion antiporter activity
Biological process: bicarbonate transport; regulation of intracellular pH; renal system process; monoatomic anion transmembrane transport; monoatomic anion transport; monoatomic ion transport; sodium ion transmembrane transport; transmembrane transport
Cellular component: apical plasma membrane; basolateral plasma membrane; membrane; plasma membrane
Genetic constraint (gnomAD): Loss-of-function variants: 95 observed, 124.25 expected, observed/expected ratio (o/e) 0.76, 90% interval 0.65 to 0.91. The upper end of that interval is the gene's LOEUF score, 0.91, which puts it in group 3 of 6, group 1 being the genes least tolerant of losing a copy. Missense variants: 1,259 observed, 1,523.8 expected, observed/expected ratio (o/e) 0.83, 90% interval 0.79 to 0.87. Synonymous variants: 550 observed, 597.82 expected, observed/expected ratio (o/e) 0.92, 90% interval 0.86 to 0.99.
Homologues: Orthologues: chimpanzee SLC4A5 (99% identical), macaque SLC4A5 (99% identical), rabbit SLC4A5 (94% identical), guinea pig SLC4A5 (93% identical), pig SLC4A5 (92% identical), mouse Slc4a5 (91% identical), dog SLC4A5 (90% identical), rat Slc4a5 (89% identical), tropical clawed frog slc4a5 (74% identical), zebrafish slc4a5a (69% identical), zebrafish slc4a5b (66% identical), Caenorhabditis elegans abts-1 (42% identical), and 3 more. Paralogues in human: SLC4A4 (60% identical), SLC4A10 (47% identical), SLC4A7 (46% identical), SLC4A8 (45% identical), SLC4A9 (42% identical), SLC4A3 (33% identical), SLC4A2 (33% identical), SLC4A1 (30% identical), SLC4A11 (19% identical).
Diseases named in the same sentence as SLC4A5 in open-access papers:
SLC4A5 is named in the same sentence as 17 diseases in open-access papers, as found by Europe PMC text mining. Sharing a sentence is not in itself a finding about the gene and the disease. The quoted sentences say what the papers report.
Hypertension (10 papers, 2012 to 2023). The presence of chronic increased pressure in the systemic arterial system. "Studies have found that the SLC4A5 gene, responsible for encoding a sodium bicarbonate transporter in the kidney, is associated with hypertension and salt sensitivity." (PMID 37416924, 2023). "A number of studies have pointed out that there is a genetic association between SLC4A5 gene polymorphism and hypertension." (PMID 35651949, 2022). "In metabolism, such as previous studies have demonstrated that single nucleotide polymorphisms (SNPs) of the sodium-bicarbonate cotransporter gene (SLC4A5) are associated with hypertension." (PMID 36277897, 2022). "Consistent with the involvement of renal Na+ retention in the hypertensive phenotype of NBCe2 deficient mice, two of the SLC4A5 SNPs associated with hypertension in humans were also found to associate with salt-sensitivity of the raised blood pressure." (PMID 24399970, 2013). "Other groups addressing African Americans have found that single-nucleotide polymorphisms (SNPs) on SLC4A5, a sodium bicarbonate transporter gene found on chromosome 2, were also significantly associated with hypertension." (PMID 24303212, 2013). "In a population survey, it was found that people with hypertension have a higher risk of gallstones than the general population, which may be related to the mutation of SLC4A5 gene loci." (PMID 35651949, 2022). "Therefore, although increased activity of NHE3 is also associated with hypertension, the salt sensitivity associated with SLC4A5 rs7571842 may indeed be due to a gain in its function." (PMID 29642240, 2018). "Individuals with these genetic variations had reduced expression of the SLC4A5 gene and decreased renal bicarbonate reabsorption, which may contribute to the development of salt sensitivity and hypertension." (PMID 37416924, 2023). "Conversely, the presence of certain SNPs (such as SLC4A5 rs8179526) may be protective against the development of hypertension among African American women even when dietary sodium is elevated." (PMID 24303212, 2013). "In addition, SLC4A5 is a member of the same family of solute carriers as SLC4 and was also shown to be associated with blood pressure and with hypertension." (PMID 22479346, 2012). "SLC4A5 variants are also highly associated with salt sensitivity, independent of hypertension." (PMID 29642240, 2018). "However, a second SLC4A5 study, utilizing a different KO mouse, caused arterial hypertension but no altered ventricular volume." (PMID 30541599, 2018). "To determine the role of renal NBCe2 in the development of hypertension, we generated CNT and intercalated cell NBCe2 knockout mice by crossing an Slc4a5 lox mouse with mice expressing cre recombinase under the V-ATPase B1 subunit promotor." (PMID 32547422, 2020).
breast carcinoma (2 papers, 2014 to 2022). "However, some general trends are observed across all breast cancer subtypes: SLC4A1, SLC4A4, SLC26A3, and SLC26A4 seem to be consistently down-regulated, while SLC4A5 is up-regulated, in all breast cancer subtypes compared to normal breast tissue." (PMID 24795638, 2014).
diabetes (2 papers, 2008 to 2022). "Three SNP−risk factor interactions were identified: the rs1042713 polymorphism of the ADRB2 Gly16 gene interacting with lipoprotein (Lp)(a), and the rs828853 and rs1299142 polymorphisms of the SLC4A5 gene interacting with diabetes mellitus (DM)." (PMID 36142394, 2022). "Only three SNP-risk factor interactions passed all three criteria – specifically, ADRB2_rs1042713 interacting with Lp(a) and SLC4A5 polymorphisms interacting with diabetes." (PMID 18482449, 2008). "Namely, two SNPs within the SLC4A5 gene (rs828853 and rs12991424) interacted with diabetes, and one SNP within the ADRB2 gene (rs1042713) interacted with Lp(a)." (PMID 18482449, 2008).
gallstones (1 paper, 2022). Solid crystalline precipitates in the biliary tract, usually formed in the gallbladder, resulting in the condition of cholelithiasis. "Our results showed that SNV05997 in SLC4A5 gene is a risk factor for GD in Tibetan people, and it is speculated that the dietary structure of Tibetan people may induce the mutation of SLC4A5 gene, and changing diet may play a certain role in the prevention of gallstone." (PMID 35651949, 2022). "These loci are located in seven different genes, including SLC4A5, MUC4, FTO, NPC1 and FXYD2 genes that may increase the risk of gallstone in the Tibetan population, while CFTR and ADCY2 genes that reduce the risk of gallstone in the Tibetan population." (PMID 35651949, 2022).
Retinal dysplasia (1 paper, 2022). Abnormal growth and differentiation, structure and appearance of the retina present from birth. "It would be of interest to examine whether canine SLC4A5 or other known regulators of RPE fluid flow are altered in drd1 and drd2 canines exhibiting retinal dysplasia." (PMID 35216333, 2022).
cancer (2 papers, 2013 to 2020). A tumor composed of atypical neoplastic, often pleomorphic cells that invade other tissues. "These transporters, including the Na+/H+ exchanger NHE1 (SLC9A1) and the Na+, HCO3- cotransporters NBCn1 (SLC4A7) and NBCe2 (SLC4A5) confer additional advantages to the cancer cells, including stimulation of proliferation, survival, and invasiveness, leading to increased tumor growth and metastasis." (PMID 32457840, 2020).
SLC4A5 also shares sentences with these, for which no sentence is quoted: Anxiety (1 paper); depression (1); distal renal tubular acidosis (1); glioblastoma (1); gout (1); Hydrocephalus (1); melanoma (1); metabolic syndrome (1); prostate carcinoma (1); retinal detachment (1); tumor (1).